INS (insulin)
Diseases named in the same sentence as INS in open-access papers (continued):
Sharing a sentence is not in itself a finding about the gene and the disease.
Hypoglycemia (continued). "This approach is supported by the results of the BEYOND trial, showing that it is possible and safe to switch from a basal-bolus regimen to a once-daily fixed-combination injection added to BI, with similar glucose control, fewer insulin doses, fewer injections daily, and less hypoglycemia." (PMID 38767675, 2024). "Thus, it appears that insulin plays a dual role, acting as an antioxidant while potentially instigating oxidant stress in patients through hypoglycemia." (PMID 39004753, 2024). "In contrast, prenatal cortisol infusion induced adrenal hypo-responsiveness in adulthood with significantly reduced cortisol responses to insulin-induced hypoglycaemia and exogenous adrenocorticotropic hormone (ACTH) administration relative to saline treatment." (PMID 38109257, 2024). "The use of glucagon to treat insulin-induced hypoglycemia is not expected to increase the risk of adverse pregnancy outcome." (PMID 39296666, 2024). "Cases of both disturbances of insulin levels and insulin-independent hypoglycemia are described." (PMID 41542255, 2024). "Postoperative hypoglycemia in patients without insulin administration is rare and has no known cause." (PMID 38393097, 2024). "We separately investigated the prognostic significance of hypoglycemia on mortality during the initial intravenous insulin therapy phase and during the later subcutaneous insulin therapy phase, both during hospitalization and in the long term (median follow-up, 652 days; range 2–3460 days)." (PMID 38594758, 2024). "This factor can bind to insulin and IGF-I receptors, mimicking endogenous insulin effects, increasing glucose uptake by tissues, and inhibiting growth hormone secretion and its hypoglycemia regulatory response, resulting in hypoglycemia and, in severe cases, epilepsy." (PMID 39416460, 2024). "Intranasal insulin has emerged as a promising method for bypassing the blood–brain barrier without causing systemic side effects like hypoglycemia." (PMID 39458902, 2024). "The use of insulin and sulfonylurea is also one of the predictors of hypoglycemia." (PMID 38243951, 2024). "Many studies of insulin technologies do not include people who are at risk of hypoglycaemia, that is, people with a history of SH or IAH, and so it can be difficult to comment on the impact of these devices on the risk of IAH." (PMID 38875308, 2024). "Occurrence of hypoglycemia in severe malaria may result from increased glucose consumption by parasitized red blood cells, impaired hepatic gluconeogenesis, and altered insulin secretion." (PMID 39146283, 2024). "GLP-1ra enhance glycaemic control by stimulating insulin secretion and by a glucose-dependent inhibition of glucagon release, resulting in effective glucose lowering without increased risk of hypoglycaemia." (PMID 38894744, 2024). "Furthermore, basal insulin doses can be automatically stopped in the face of impending hypoglycemia." (PMID 38785359, 2024). "There was a tendency toward a higher frequency and longer duration of use for Ease-off with Lyumjev, suggesting that users may have felt the need to prevent hypoglycemia more often when using Lyumjev compared with insulin lispro." (PMID 39422158, 2024). "Furthermore, some studies have reported that diabetic rats required very high insulin concentrations (30–40 IU/kg) to induce hypoglycaemia (via i.p. injections)." (PMID 38392992, 2024). "However, it is important to note that even with increased basal insulin and weight gain, there was a decrease in overall hypoglycemia rates and, at least, comparable efficacy." (PMID 38982528, 2024). "In contrast, all C3H mice without hypoglycemia showed loss of signals in the bioluminescence images and insulin-positive cells in the grafts, implying MIN6 cell rejection." (PMID 38920672, 2024). "However, some patients suffer from high day-to-day GV and hypoglycemia, despite the use of subcutaneous multiple insulin injection therapy." (PMID 38541176, 2024).
Hypoglycemia (continued). "Given their superior or comparable efficacy in reducing HbA1c, coupled with additional benefits such as weight loss and a low risk of hypoglycemia, GLP-1 RAs are increasingly recommended as the preferred first-line injectable therapy for T2DM, often even before insulin." (PMID 39720384, 2024). "Increased insulin-independent glucose uptake and reduced counterregulatory responses may also contribute to hypoglycemia in patients with PBH." (PMID 39264731, 2024). "On the other hand, hypoglycemia and injection sit reaction were more common with weekly insulin." (PMID 39335457, 2024). "High-dose (5 IU kg–1) SC-INS induced hypoglycaemia (BG < 3.0 mmol l–1), whereas oral insulin did not cause hypoglycaemia even at 300 IU kg–1." (PMID 38168926, 2024). "Moreover, serum insulin levels were low during these episodes along with C-peptide levels, cortisol however was elevated, Also, it is worth mentioning that the hypoglycemia episodes were unrelated to the hemodialysis sessions." (PMID 39040763, 2024). "These lower hypoglycemia findings with efsitoracompared to icodec could be the result of differences in study design, glycemic control,and/or insulin titrations or perhaps influenced by efsitora's flat PK profile." (PMID 38224978, 2024). "However, among the 243 patients prescribed insulin (glargine, detemir, degludec, Aspart, regular, NPH), 65 patients experienced hypoglycemia, and this association was found to be statistically significant (p = 0.016)." (PMID 39208059, 2024). "In patients with renal failure, for example, insulin clearance is reduced so that higher insulin levels could lead to severe hypoglycemia." (PMID 38397994, 2024). "Hypoglycemia is a common complication of insulin-based hyperkalemia treatment." (PMID 39274318, 2024). "Switching from insulin to sulfonylurea-based therapy after genetic diagnosis of ABCC8-MODY has been associated with improved C-peptide levels and metabolic control, and lower rates of hypoglycemia." (PMID 38980630, 2024). "During the monthly 5-day diet cycle, daily glucose measurements (self-measurement) resulted in 2 reported occurrences of hypoglycemia (<4.0 mmol/L) upon continued use of SU-derivates or long acting insulin, of which one patient discontinued due this occurrence of hypoglycemia." (PMID 38600065, 2024). "While the morbidity associated with insulin/dextrose has been demonstrated previously, this QIP was able to demonstrate a ‘real-world’ reduction in iatrogenic hypoglycaemia secondary to insulin/dextrose, through simple interventions and the introduction of SZC." (PMID 38871123, 2024). "However, the combination of metformin with insulin resulted in a significant decrease in neonatal hypoglycemia (metformin plus insulin: 7.8%, insulin alone: 30%, p < 0.01)." (PMID 37798604, 2024). "However, of the 14 studies focusing on insulin bolus calculators, or glucose or hypoglycemia prediction, only 4 (29%) involved more than 10 patients in the training sample, with 141 being the largest sample size." (PMID 38241075, 2024). "Specific hepatic targeting of insulin may also be key to the reduced episodes of hypoglycaemia and reduce the adverse effects of hyperinsulinaemia compared with parenteral administration of animals such as weight gain and insulin resistance." (PMID 38168926, 2024). "Therefore, CGM use is an important tool to help prevent hypoglycemia during or after exercise, understand how different foods influence insulin sensitivity and therefore optimize pre-exercise/competition nutrition." (PMID 39171092, 2024). "Lixisenatide stimulates insulin secretion when blood glucose is elevated but not when blood glucose is normal, thereby circumventing the risk of hypoglycemia and glucose-dependently inhibiting glucagon secretion." (PMID 39598478, 2024).
Hypoglycemia (continued). "These include intensive insulin therapy, subcutaneous insulin administration leading to peripheral hyperinsulinemia, repetitive episodes of hypoglycemia, and the consequences of a fear of hypoglycemia in the form of frequent snacking and decreased physical activity." (PMID 39335526, 2024). "Our findings also suggest that HIIT may improve the glucagon response to insulin-induced hypoglycaemia." (PMID 38010533, 2024). "These may include concerns regarding patient acceptance, fear of hypoglycemia, perceived complexity of insulin regimens, and time constraints during consultations." (PMID 38559691, 2024). "Moreover, stopping insulin infusions when a low blood glucose value is encountered helps to avoid hypoglycemia and to re-start hypoglycemic symptoms." (PMID 38894740, 2024). "Advising insulin dose changes based on an incorrect assumption that an individual is following the prescribed insulin treatment can potentially lead to overtreatment and hypoglycaemia." (PMID 39138689, 2024). "This is compatible with a previous Saudi study where it was found that the most common risk factor associated with hypoglycemia was eating after a long period of insulin intake, and the most common symptoms of hypoglycemia were tremors, sweating, palpitations, and drowsiness." (PMID 39583394, 2024). "When insulin separates from these antibodies, hypoglycemia occurs." (PMID 39575003, 2024). "Lower circulating insulin levels may help reduce the risk of hypoglycemia both during and after EXE, especially when insulin sensitivity is enhanced." (PMID 38542818, 2024). "For older patients treated with sulfonylurea drugs or insulin, the use of CGM to assess the risk of hypoglycemia may be considered." (PMID 38571669, 2024). "Hypoglycemia is less frequent following IV insulin discontinuation with early glargine, but the IV insulin rate may need to be reduced to minimize hypoglycemia during IV insulin infusion." (PMID 39136541, 2024). "However, when the glucose blood level falls below 14.0 mmol/L, a dextrose infusion is suggested to prevent hypoglycemia and to act as the substrate for insulin." (PMID 38786741, 2024). "SMBG promotes insulin titration and correction of hyper- and hypoglycemia." (PMID 37996773, 2024). "The diagnosis of insulinoma can be challenging, requiring documentation of hypoglycaemia associated with non-suppressed insulin and C-peptide, often achieved during a prolonged 72 h fast performed in inpatient setting." (PMID 38451386, 2024). "The authors used insulin implants in diabetic rats that could potentially lead to undocumented antecedent hypoglycaemia." (PMID 38392992, 2024). "The primary objective was to compare the incidence of hypoglycemia after treatment with insulin between patients with reduced kidney function on hemodialysis and their counterparts (who are not hemodialysis-dependent), as well as the risk factors associated with it." (PMID 39274318, 2024). "Simultaneously, it reduces insulin dosage, promotes weight loss, significantly decreases the occurrence of severe hypoglycemia, and does not increase the probability of hypoglycemia occurrence." (PMID 38694909, 2024). "The incidence of severe hypoglycemia in the liraglutide and placebo groups was comparable, suggesting that liraglutide did not raise the risk of hypoglycemia when used in conjunction with insulin therapy." (PMID 39273299, 2024). "There does not appear to be a greater risk of level 2 hypoglycemia, and this risk does not continue after discontinuation of the IV insulin." (PMID 39136541, 2024). "The prolonged insulin response leads to hypoglycemia in the second to third hours after meals." (PMID 38337532, 2024). "The closed-loop group had a significantly higher TIR (69.0% in the AID group vs 31.5% in the conventional insulin therapy group) without increasing the risk of hypoglycaemia." (PMID 39112642, 2024).
Hypoglycemia (continued). "In one large trial evaluating the incidence of hypoglycemia using self-monitoring of blood glucose and/or interstitial continuous glucose monitors, it was found that −56% of T2D patients on insulin had hypoglycemic events, as defined as a glucose ≤60 mg/dL, over a 72-h observational period." (PMID 38510652, 2024). "Adjusting insulin doses and changing glycemic targets may be necessary in children with frequent hypoglycemia." (PMID 38894740, 2024). "For diabetic patients with gastroparesis, treatment with insulin induces hypoglycemia and a higher risk of hypoglycemia compared to patients without gastroparesis." (PMID 39450111, 2024). "Indeed, adenosine has been shown to offer neuroprotection in models of ischemia, traumatic brain injury and insulin-induced hypoglycemia." (PMID 39338322, 2024). "This could expose the patient to insulin overtreatment, resulting in hypoglycemia and the possibility of developing seizures, unconsciousness, or death." (PMID 39000136, 2024). "With these objectives in mind, we successfully developed a male rodent model of late-stage T2D characterized by significantly higher HbA1c, insulin resistance and defective glucagon counterregulation to insulin-induced hypoglycemia compared to HFF and NCF controls." (PMID 38510652, 2024). "Although insulin is very effective in DM, it may lead to severe hypoglycemia, dizziness, sweating, palpitations, headache, blurred vision, and abdominal pain." (PMID 39519546, 2024). "Rapid weight loss and regression of insulin resistance after bariatric surgery may lead to a slower normalization of insulin production, contributing to hypoglycemia." (PMID 39555226, 2024). "A pilot study conducted on 21 subjects with postprandial hypoglycemia showed that canagliflozin (300 mg/day) significantly reduced blood glucose and insulin levels 60 min after a meal following the intake of 100 g of glucose during an oral glucose tolerance test in patients with previous RYGB." (PMID 38942960, 2024). "Although intensive insulin therapy could improve certain outcomes, the higher incidence of hypoglycemia could negate these benefits." (PMID 39199594, 2024). "Additionally, the occurrence of comorbidities, episodes of hypoglycemia, and the requirement for insulin treatment further complicate patients’ experiences." (PMID 39553423, 2024). "Some authors hypothesized that this deleterious impact was driven by severe hypoglycemia events, which were more often seen in patients treated with insulin than those treated with other therapies." (PMID 39434474, 2024). "Digital tools were frequently implemented across the sites for DM, where clinicians utilised a novel decision-support app (Thinksulin), as well as targeted online modules (e.g., insulin management, hypoglycaemia) to increase the skill of nurses and junior medical officers." (PMID 38448960, 2024). "The implication is that delayed gastric emptying reduces the initial insulin requirement following a meal, and when markedly delayed, it may increase the propensity for insulin-induced hypoglycemia." (PMID 39568409, 2024). "In particular, insulin overdose can occur in individuals who do not account for exercise events when determining the necessary insulin doses or who neglect to include exercise in insulin pump settings during pump therapy, potentially resulting in episodes of severe hypoglycemia." (PMID 38676028, 2024). "In particular, nowadays, icodec insulin is a candidate to become the primary basal weekly insulin, increasing patient compliance because of its tolerability and encouraging safety results related to hypoglycemia." (PMID 38672255, 2024). "If hypoglycemia is detected, longer duration basal insulin-analogues, offering lower day-to-day glycemic variation and lower risk of hypoglycemia, may be considered." (PMID 38116986, 2024).
Hypoglycemia (continued). "When it is not observed by clinicians, a prolonged supervised fasting test, which can last up to 72 h, has been established as the gold-standard method for the assessment of the role of insulin secretion pattern in hypoglycaemia occurring in the fasting period." (PMID 38451386, 2024). "While there are very few studies which have investigated the effects of insulin-induced hypoglycaemia on neuropeptides in the adrenal gland, current evidence suggests that recurrent insulin-induced hypoglycaemia increases protein expression of neuropeptides such as NPY, galanin, and proenkephalin." (PMID 38392992, 2024). "A novel finding in this study is that treatment with α-lipoic acid in the Akt-dependent phosphorylation site on mTOR is a strong steatohepatitis protector, leading to enhanced glucose and insulin tolerance and finally hypoglycemia, which was also noticed in our previously published data." (PMID 38794739, 2024). "Although the hypothesis that insulin dose contributed to CV mortality was skeptically received, nocturnal hypoglycemia is very common and largely underdiagnosed in elderly individuals receiving insulin treatment T2D." (PMID 38592103, 2024). "Insulin breakdown may take longer, and both formulation and dosing may need to be changed to avoid hypoglycemia." (PMID 39149651, 2024). "Weeks after the headache episode, the patient was reevaluated in the emergency department with a three-day history of diffuse abdominal pain, vomiting, asthenia, myalgia, hypotension, tachycardia, orthostatism, and recurrent hypoglycemia despite insulin suspension." (PMID 39130944, 2024). "Importantly, all mice with hypoglycemia also showed positive signals in the bioluminescence images and insulin-positive cells in the grafts, indicating tolerance of the MIN6 cells." (PMID 38920672, 2024). "A hybrid closed-loop insulin delivery system could achieve increased time in target, and reductions in HbA1c, hyperglycemia, and hypoglycemia, compared to that with an insulin pump." (PMID 38541176, 2024). "A supervised fast was performed and terminated after 3 h with symptoms of hypoglycemia, a glucose level of 2.7 mmol/L, an insulin level of 10.7 mU/L (reference range 2.6–24.9 mU/L), and a C-peptide of 0.32 nmol/L (reference range 0.27–1.27), confirming endogenous hyperinsulinemic hypoglycemia." (PMID 39330031, 2024). "However, when combined with insulin or sulfonylureas, GLP-1-RAs are associated with increased vulnerability to hypoglycemia." (PMID 39355484, 2024). "Weight gain and hypoglycemia, common side effects of insulin therapy, may delay its initiation and intensification." (PMID 39629047, 2024). "U300 glargine overdose may lead to both a multimodal elevation in blood insulin levels and prolonged hypoglycemia compared to U100 glargine." (PMID 38371090, 2024). "Notably, when GLP-1RAs combined with insulin or sulfonylureas, reduced dose of these drugs is recommended to avoid hypoglycemia." (PMID 38384297, 2024). "However, research has shown that insulin therapy-induced hypoglycemia can be better detected and promptly treated in ICU patients, thereby reducing adverse events caused by low BG." (PMID 38368401, 2024). "Hypoglycemia risk stems from imperfect (non-physiologic) insulin replacement in a setting of defective glucose counterregulation." (PMID 38298268, 2023). "According to one recent RCT, preoperative administration of liraglutide stabilized the perioperative plasma glucose level and reduced the perioperative insulin requirement without increasing the risk of hypoglycemia." (PMID 36310325, 2023). "Increasing the dose of the GLP-1 receptor agonist may require a decrease in insulin dosage and adjustment or discontinuation of insulin secretagogues if hypoglycemia is a concern." (PMID 38105902, 2023).